PIK3CD (phosphatidylinositol-4,5-bisphosphate 3-kinase catalytic subunit delta)
Description:
Phosphoinositide-3-kinase (PI3K) phosphorylates phosphatidylinositol (PI) and its phosphorylated derivatives at position 3 of the inositol ring to produce 3-phosphoinositides. Uses ATP and PtdIns(4,5)P2 (phosphatidylinositol 4,5-bisphosphate) to generate phosphatidylinositol 3,4,5-trisphosphate (PIP3). PIP3 plays a key role by recruiting PH domain-containing proteins to the membrane, including AKT1 and PDPK1, activating signaling cascades involved in cell growth, survival, proliferation, motility and morphology. Mediates immune responses. Plays a role in B-cell development, proliferation, migration, and function. Required for B-cell receptor (BCR) signaling. Mediates B-cell proliferation response to anti-IgM, anti-CD40 and IL4 stimulation. Promotes cytokine production in response to TLR4 and TLR9. Required for antibody class switch mediated by TLR9. Involved in the antigen presentation function of B-cells. Involved in B-cell chemotaxis in response to CXCL13 and sphingosine 1-phosphate (S1P). Required for proliferation, signaling and cytokine production of naive, effector and memory T-cells. Required for T-cell receptor (TCR) signaling. Mediates TCR signaling events at the immune synapse. Activation by TCR leads to antigen-dependent memory T-cell migration and retention to antigenic tissues. Together with PIK3CG participates in T-cell development. Contributes to T-helper cell expansion and differentiation. Required for T-cell migration mediated by homing receptors SELL/CD62L, CCR7 and S1PR1 and antigen dependent recruitment of T-cells. Together with PIK3CG is involved in natural killer (NK) cell development and migration towards the sites of inflammation. Participates in NK cell receptor activation. Plays a role in NK cell maturation and cytokine production. Together with PIK3CG is involved in neutrophil chemotaxis and extravasation. Together with PIK3CG participates in neutrophil respiratory burst. Plays important roles in mast-cell development and mast cell mediated allergic response. Involved in stem cell factor (SCF)-mediated proliferation, adhesion and migration. Required for allergen-IgE-induced degranulation and cytokine release. The lipid kinase activity is required for its biological function. Isoform 2 may be involved in stabilizing total RAS levels, resulting in increased ERK phosphorylation and increased PI3K activity.
Synonyms: PI3Kdelta; p110delta; p110D; APDS; IMD14; IMD14A; IMD14B; PI3K; ROCHIS
Tractability: Small molecule: an approved drug acts on it; a structure with a bound ligand is known; a high-quality ligand is known; it belongs to a druggable protein family. Antibody: its Gene Ontology location is reachable by antibodies, with high confidence. PROTAC: ubiquitination databases record sites on it; its protein half-life has been measured; a small molecule that binds it is known.
Target class: Enzyme; Transferase
Chemical probes: APITOLISIB (high quality), CHEMBL2171944, CHEMBL3403664, CHMFL-PI3KD-317, FD223, FMF-02-063-1 (high quality), IDELALISIB (high quality), PD084093, PD084151, PD134667, PD134713, PD134714, PD134716, PD134718, PD134719, PD134721, PD134725, PI-3065 (high quality), PICTILISIB (high quality), leniolisib (high quality)
Gene: Protein-coding gene on chromosome 1 (9,629,889 to 9,730,117, forward strand). Ensembl gene ENSG00000171608.
Subcellular location: Cytoplasm
Subcellular location (Human Protein Atlas): Vesicles; Cytokinetic bridge; Cytosol; Microtubules; Primary cilium; Primary cilium tip
Pathways (Reactome):
Immune System: Antigen activates B Cell Receptor (BCR) leading to generation of second messengers; CD28 dependent PI3K/Akt signaling; Co-stimulation by ICOS; Interleukin receptor SHC signaling; Interleukin-3, Interleukin-5 and GM-CSF signaling; Regulation of signaling by CBL; Signaling by CSF1 (M-CSF) in myeloid cells
Signal Transduction: Erythropoietin activates Phosphoinositide-3-kinase (PI3K); PI5P, PP2A and IER3 Regulate PI3K/AKT Signaling; PIP3 activates AKT signaling
Cellular responses to stimuli: High laminar flow shear stress activates signaling by PIEZO1 and PECAM1:CDH5:KDR in endothelial cells
Developmental Biology: RET signaling
Disease: Constitutive Signaling by Aberrant PI3K in Cancer
Metabolism: Synthesis of PIPs at the plasma membrane
Gene Ontology:
Molecular function: protein binding; 1-phosphatidylinositol-3-kinase activity; 1-phosphatidylinositol-4,5-bisphosphate 3-kinase activity; 1-phosphatidylinositol-4-phosphate 3-kinase activity; kinase activity
Biological process: phosphatidylinositol 3-kinase/protein kinase B signal transduction; positive regulation of cell migration; positive regulation of endothelial cell migration; positive regulation of endothelial cell proliferation; positive regulation of epithelial tube formation; positive regulation of gene expression; positive regulation of neutrophil apoptotic process; vascular endothelial growth factor signaling pathway; adaptive immune response; B cell activation; B cell chemotaxis; B cell differentiation; B cell receptor signaling pathway; cell migration; immune response; inflammatory response; innate immune response; mast cell chemotaxis; mast cell degranulation; mast cell differentiation; natural killer cell activation; natural killer cell chemotaxis; natural killer cell differentiation; neutrophil chemotaxis; neutrophil extravasation; and 20 more
Cellular component: cytosol; phosphatidylinositol 3-kinase complex, class IA; phosphatidylinositol 3-kinase complex; plasma membrane; cytoplasm
Genetic constraint (gnomAD): Loss-of-function variants: 20 observed, 126.24 expected, observed/expected ratio (o/e) 0.16, 90% interval 0.11 to 0.23. The upper end of that interval is the gene's LOEUF score, 0.23, which puts it in group 1 of 6, group 1 being the genes least tolerant of losing a copy. Missense variants: 787 observed, 1,455 expected, observed/expected ratio (o/e) 0.54, 90% interval 0.51 to 0.57. Synonymous variants: 596 observed, 618.66 expected, observed/expected ratio (o/e) 0.96, 90% interval 0.9 to 1.03.
Gene-disease validity (ClinGen):
ClinGen rates the evidence that PIK3CD causes each of these diseases.
immunodeficiency 14 (autosomal dominant): Definitive.
immunodeficiency 14b, autosomal recessive (autosomal recessive): Definitive.
Homologues: Orthologues: macaque PIK3CD (99% identical), pig PIK3CD (96% identical), chimpanzee PIK3CD (96% identical), dog PIK3CD (95% identical), mouse Pik3cd (95% identical), rabbit PIK3CD (94% identical), rat Pik3cd (94% identical), guinea pig PIK3CD (93% identical), zebrafish pik3cd (70% identical), Drosophila melanogaster Pi3K92E (40% identical), Caenorhabditis elegans age-1 (28% identical), Drosophila melanogaster Pi3K68D (24% identical), and 1 more. Paralogues in human: PIK3CB (58% identical), PIK3CA (41% identical), PIK3CG (32% identical), PIK3C2B (28% identical), PIK3C2A (27% identical), PIK3C2G (23% identical), PIK3C3 (21% identical), PI4KA (20% identical), PI4KB (14% identical).
Diseases named in the same sentence as PIK3CD in open-access papers:
PIK3CD is named in the same sentence as 188 diseases in open-access papers, as found by Europe PMC text mining. Sharing a sentence is not in itself a finding about the gene and the disease. The quoted sentences say what the papers report.
Immunodeficiency (46 papers, 2013 to 2025). Failure of the immune system to protect the body adequately from infection, due to the absence or insufficiency of some component process or substance. "This condition occurs because of gain-of-function mutations in the PIK3CD or PIK3R1 genes, which encode the catalytic (p110δ) and regulatory (p85α) subunits of the delta isoform, respectively, resulting in immune dysfunction." (PMID 40978950, 2025). "GOF mutations in the p110δ subunit of PIK3CD cause an immunodeficiency characterized by recurrent infections leading to structural lung abnormalities including bronchiectasis, lymphoproliferation, and EBV or CMV viremia." (PMID 38287413, 2024). "in a study that described GOF mutations in the PIK3CD gene, which encodes the p110δ catalytic subunit of Phosphoinositide 3‐kinase delta (PI3Kδ), as the cause of a combined immunodeficiency syndrome." (PMID 40625457, 2024). "Of those, PIK3CD encodes p110δ to play critical roles in adaptive immunity responsible for senescent T cells, lymphadenopathy and immunodeficiency." (PMID 37605313, 2023). "The variant in PIK3CD (c.1429 G > A) is a novel mutation that can cause immunodeficiency in patients." (PMID 37475052, 2023). "This inhibitory interaction in class IA PI3Ks is disrupted in human cancers (helical hotspot mutations in PIK3CA) and immune disorders (helical mutations in PIK3CD in APDS1)." (PMID 37417733, 2023). "The present study aims to explore initial dosages in pediatric patients with PIK3CD mutation-related immunodeficiency disease." (PMID 36188573, 2022). "The present study is the first exploring this particular group of pediatric patients with PIK3CD mutation-related immunodeficiency disease." (PMID 36188573, 2022). "This is the first attempt to build a sirolimus PPK model for recommending initial dosages in children with PIK3CD mutation-related immunodeficiency disease, thereby providing a reference for individualized clinical drug administration." (PMID 36188573, 2022). "Further, the Monte Carlo method was used to simulate initial dosages of sirolimus in pediatric patients with PIK3CD mutation-related immunodeficiency disease based on the final model, and where the target concentration window of sirolimus was 5–15 ng/ml." (PMID 36188573, 2022). "Without posaconazole, the initial dosages of sirolimus were 0.07, 0.06, 0.05, and 0.04 mg/kg/day for body weights of 10–14, 14–25, 25–50, and 50–60 kg in pediatric patients with PIK3CD mutation-related immunodeficiency disease, respectively." (PMID 36188573, 2022). "There is thus an urgent need to provide an accurate and individualized sirolimus administration regimen for the treatment of pediatric patients with PIK3CD mutation-related immunodeficiency disease." (PMID 36188573, 2022). "The present study aims to explore the initial dosage of sirolimus in children with PIK3CD mutation-related immunodeficiency disease." (PMID 36188573, 2022). "This is the first effort to build a sirolimus PPK model and recommend the initial dosages in pediatric patients with PIK3CD mutation-related immunodeficiency disease." (PMID 36188573, 2022). "Among them, sirolimus, which directly targets mTOR and inhibits the downstream of the PI3K pathway, is currently available as one of the specific therapeutic methods used in clinical practice for children with PIK3CD mutation-related immunodeficiency disease." (PMID 36188573, 2022). "A total of 24 pediatric patients with PIK3CD mutation related-immunodeficiency disease were included, 16 boys and 8 girls, whose ages were from 2.15–17.92 years and weight from 10–63 kg." (PMID 36188573, 2022). "Overall, due to the lower morbidity of PIK3CD mutation-related immunodeficiency disease, the number of pediatric patients included in the present study is small." (PMID 36188573, 2022). "Sirolimus is used to treat pediatric patients with PIK3CD mutation-related immunodeficiency disease." (PMID 36188573, 2022).
Immunodeficiency (continued). "Mutations, activation, and low expression of PIK3CD were associated with autoimmune diseases and immunodeficiency." (PMID 33396684, 2020). "The clinical and immunophenotypes of PIK3CD mutation-related immunodeficiency disease are variable, from mild to asymptomatic in adulthood, to fatal immunodeficiency in childhood, and the most common manifestations are recurrent respiratory tract infections and immune disorders." (PMID 36188573, 2022). "Hence, the present study recommends initial dosages of sirolimus in pediatric patients with PIK3CD mutation-related immunodeficiency disease based on PPK and a Monte Carlo simulation." (PMID 36188573, 2022). "For pediatric patients with PIK3CD mutation-related immunodeficiency disease with posaconazole, the concentrations from dosages of 0.02 mg/kg/day sirolimus were all within the treatment window, and there was no value exceeding the upper limit of the target concentration." (PMID 36188573, 2022). "Moreover, our assay was able to detect APDS caused by gain of function in PIK3CD which is a common variable immunodeficiency (CVID) with low TREC and KREC levels." (PMID 32765500, 2020). "Moreover, we and others have reported immunodeficiency caused by heterozygous, gain-of-function mutations in the leukocyte-restricted PIK3CD or ubiquitously expressed PIK3R1 gene, each encoding a subunit of the PI3Kδ complex." (PMID 31554793, 2019). "Moreover, activating mutations in PIK3CD encoding p110δ cause a human immunodeficiency known as activated PI3K delta syndrome (APDS), which is associated with chronically activated lymphocytes that undergo apoptosis or senescence." (PMID 28713374, 2017). "Activated PI3Kδ syndrome (APDS) is caused by variants in the PIK3CD or PIK3R1 genes, resulting in hyperactivity of the AKT-mTOR-PI3K pathway, as well as progressive immunodeficiency and/or dysregulation." (PMID 39679264, 2024). "Here, we report a family with inherited immunodeficiencies in CD137 and PIK3CD, three members of which have T or NK cell-associated EBV." (PMID 35612313, 2022). "Mutations in PIK3CD and PIK3R1, encoding the PI3K p110δ and p85α subunits, respectively, cause increased PI3K activity and result in immunodeficiency with immune dysregulation." (PMID 30891027, 2019). "Recently described autosomal dominant gain-of-function (GOF) mutations in PIK3CD and PIK3R1 cause combined immunodeficiencies that can also present as CSR/HIGM defects." (PMID 30319630, 2018). "Diseases involving the PI3K pathway due to PIK3CD and PIK3R1 GOF mutations, have recently been highlighted as forms of combined immunodeficiency compromising both the T- and B-cell compartments." (PMID 30319630, 2018). "In addition, bi-allelic loss-of-function (LOF) mutations in PIK3CD leads to immunodeficiency 14B (OMIM #619,281), Therefore, too little or too much PI3Kδ activity would lead to immunodeficiency." (PMID 38287413, 2024). "PIK3R2 also interacts with the catalytic active PIK3CD (phosphatidylinositol-4,5-bisphosphate 3-kinase catalytic subunit delta), which is implicated in the phosphoinositide 3-kinase δ syndrome (APDS) associated with senescent T cells, lymphadenopathy, and immunodeficiency." (PMID 31311583, 2019). "It is likely that additional mutations in PIK3CD will be discovered that mimic previously discovered oncogenic mutations in PIK3CA, highlighting the need to sequence the entire PIK3CD gene in patients presenting with complex immunodeficiencies." (PMID 29616047, 2018). "However, the drug interaction between posaconazole and sirolimus in children with PIK3CD mutation-related immunodeficiency disease has not been reported." (PMID 36188573, 2022). "For pediatric patients with PIK3CD mutation-related immunodeficiency disease without posaconazole, the probabilities of exceeding the upper limit of the target concentration were less than 9%, 8%, 6%, and 1%, for the dosages of sirolimus, 0.07, 0.06, 0.05, and 0.04 mg/kg/day respectively." (PMID 36188573, 2022).
Immunodeficiency (continued). "Additional combined immunodeficiencies observed included activated PI3K-delta syndrome (PIK3CD 4/61) and 2 combined immunodeficiencies with no genetic mutation reported." (PMID 36211419, 2022).
breast carcinoma (25 papers, 2009 to 2025). "Kaplan–Meier survival analysis correlated gene expression levels with overall survival, associating decreased PIK3CD levels with worse prognosis in breast cancer and elevated CYP19A1 expression with poorer survival in colon cancer." (PMID 39204124, 2024). "As an intrinsic cancer-causing driver, PIK3CD was found in primary fibroblasts but was scarcely detectable in breast cancer cell lines." (PMID 37861728, 2023). "The results indicated that PIK3CD is associated with breast cancer." (PMID 27842518, 2016). "In TNBC and HER2-Positive breast cancer tissues, the promoter methylation level of PIK3CD was lower than in Luminal." (PMID 37861728, 2023). "MiR-199a-5p mimic significantly downregulated TGF-β2 (p = 0.0317) and PIK3CD expression (p = 0.0079) in MDA-MB-231 breast cancer cell line." (PMID 27842518, 2016). "PIK3CD is expressed mainly in leucocytes; however, the expression of PIK3CD was also evidenced in non-leucocyte cancer cell lines, including breast carcinoma, melanoma and glioma." (PMID 25366420, 2015). "Results suggested that PIK3CD expression were higher in the circulation (p = 0.0453) and TGF-β2 had no observable changes in breast cancer patients when compared to normal control." (PMID 27842518, 2016).
chronic lymphocytic leukemia (24 papers, 2011 to 2023). "On the other hand, B cell signaling is upregulated in chronic lymphocytic leukemia through the hyperactivation of the PI3K pathway due to increased expression of PIK3CD protein product p110δ in hematopoietic cells and lymphoid tissue." (PMID 33147762, 2020). "A PIK3CD/p110δ inhibitor idelalisib had achieved a plausible clinical outcome in treating chronic lymphocytic leukemia (CLL)." (PMID 29326882, 2017). "PIK3CD (PI3K-delta p110 catalytic subunit) has been shown to have roles in BCR-ABL-mediated chronic lymphocytic leukemia (CLL) by turning off breakpoint cluster region (BCR) signaling." (PMID 24931005, 2014). "In lymphomas, PIK3CA has been reported to be amplified in 15/22 (68%) cases of mantle cell lymphoma (MCL), 9/161 (5.6%) cases of chronic lymphocytic leukemia (CLL), and mutated in 1/76 (1.3%) cases of DLBCL; while PIK3CD has been reported to be mutated in 3/73 (4.1%) cases of DLBCL." (PMID 24418330, 2014).